PCDHB6 (protocadherin beta 6)
Description:
Calcium-dependent cell-adhesion protein involved in cells self-recognition and non-self discrimination. Thereby, it is involved in the establishment and maintenance of specific neuronal connections in the brain.
Synonyms: PCDH-BETA6
Tractability: Antibody: its Gene Ontology location is reachable by antibodies, with high confidence; UniProt places it where antibodies can reach, with medium confidence; UniProt predicts a signal peptide or a membrane-spanning region.
Gene: Protein-coding gene on chromosome 5 (141,150,057 to 141,153,287, forward strand). Ensembl gene ENSG00000113211.
Subcellular location: Cell membrane
Subcellular location (Human Protein Atlas): Nucleoplasm
Gene Ontology:
Molecular function: calcium ion binding; cell adhesion molecule binding; identical protein binding
Biological process: calcium-dependent cell-cell adhesion; cell adhesion; cell-cell recognition; chemical synaptic transmission; homophilic cell-cell adhesion; nervous system development; synapse assembly
Cellular component: membrane; plasma membrane; synapse
Genetic constraint (gnomAD): Missense variants: 1,137 observed, 1,034.2 expected, observed/expected ratio (o/e) 1.1, 90% interval 1.05 to 1.15. Synonymous variants: 506 observed, 466.05 expected, observed/expected ratio (o/e) 1.09, 90% interval 1.01 to 1.17.
Homologues: Orthologues: chimpanzee PCDHB6 (98% identical), macaque PCDHB6 (95% identical), dog PCDHB6 (83% identical), mouse Pcdhb13 (78% identical). Paralogues in human: PCDHB5 (77% identical), PCDHB3 (77% identical), PCDHB4 (77% identical), PCDHB2 (76% identical), PCDHB15 (76% identical), PCDHB16 (75% identical), PCDHB14 (75% identical), PCDHB13 (74% identical), PCDHB8 (73% identical), PCDHB9 (73% identical), PCDHB11 (72% identical), PCDHB10 (72% identical), and 49 more.
Diseases named in the same sentence as PCDHB6 in open-access papers:
PCDHB6 is named in the same sentence as 6 diseases in open-access papers, as found by Europe PMC text mining. Sharing a sentence is not in itself a finding about the gene and the disease. The quoted sentences say what the papers report.
Cluster headache (1 paper, 2025). A type of headache characterized by repeated attacks of unilateral pain lasting 15 to 180 minutes and associated with local autonomic signs. "Lastly, they expanded their analysis to include ANO3, ITGAL, PLCE1, and PCDHB6 genes and found rs1531394 in the ANO3 gene to be significantly associated with cluster headache." (PMID 39560176, 2025).
diabetes (1 paper, 2022). "There were 8 differentially methylated genes (CDH2/PCDHB10/PCDHB11/PCDHB14/PCDHB16/PCDHB3/PCDHB6/PCDHB9) in the LAA subgroup and 1 (CDH2) in the SVD subgroup after adjusting for smoking, drinking, history of hypertension and diabetes, and blood lipid levels (p < 0.05)." (PMID 35480311, 2022).
tumor (1 paper, 2022). "In this study, PCDHB2, PCDHB4, and PCDHB6 were overexpressed in the HCCW4 subgroup, in association with worse survival; this finding contradicts a tumor suppressor role." (PMID 36230503, 2022).
PCDHB6 also shares sentences with these, for which no sentence is quoted: Hypertension (1 paper); liver cancer (1); memory impairment (1).